LY6E (lymphocyte antigen 6 family member E)
Diseases named in the same sentence as LY6E in open-access papers (continued):
Sharing a sentence is not in itself a finding about the gene and the disease.
tongue cancer (1 paper, 2019). A malignant neoplasm affecting the tongue. "Differential expression profiling of the tongue cancer cohort triaged based on the stage, pathology identified multiple candidate markers; JAM2, SMURF1, LY6E, MFN1 and SUPT16H." (PMID 31310629, 2019).
infection (30 papers, 2013 to 2025). The state of being infected such as from the introduction of a foreign agent such as serum, vaccine, antigenic substance or organism. "Altogether, the presented results show the relevance of gene Ly6E in the immune response against the infection caused by MHV." (PMID 32708319, 2020). "Variations in the abundance of expression, as well as the localization of LY6E and its associated proteins or lipids, may explain the differential effects of LY6E on the infection of different viruses in different cell types." (PMID 32641482, 2020). "Among them, Ly6e (lymphocyte antigen 6 complex, locus E) plays an important role in regulating immunity, T cell physiological characteristics and tumor formation and the increased expression of Ly6e lead to the increased risk of human infection with the virus." (PMID 33326461, 2020). "In addition to HIV-1, LY6E has been associated with enhanced infection for a number of enveloped RNA viruses." (PMID 31684192, 2019). "The LY6E protein has also been linked to enhanced infection by mouse adenovirus type 1 (MAV-1)." (PMID 31684192, 2019). "Finally, in the light of previous works, we hypothesize that Ly6E ablation might show analogous detrimental effects on immunity upon the infection caused by other viruses including SARS-CoV, MERS and SARS-CoV-2." (PMID 32708319, 2020). "The most extensively studied Ly6/uPAR protein LY6E enhances the infection of influenza A virus, flaviviruses, and human immunodeficiency virus 1, but inhibits coronavirus infection by impairing viral fusion." (PMID 40373067, 2025). "Upon infection with the four coronaviruses, knockout of LY6E led to significant increases in infection: nearly 4-fold for SARS-CoV-2, 60-fold for HCoV-OC43, 5-fold for HCoV-229E, and 10-fold for PEDV." (PMID 40901862, 2025). "Our results showed that overexpression of IFITM1, IFITM2, IFITM3, or LY6E significantly inhibited the infection of CCoV-HuPn-2018pp and HCoV-229Epp." (PMID 37676001, 2023). "This phenotype was very reminiscent of LY6E knockout, which resulted in an infection kinetic of SARS-CoV-2 that was comparable to MDM2 deletion, i.e., an early onset of the infection signal and a rapid increase of the fluorescent signal." (PMID 37632105, 2023). "Regarding this issue, it has been reported that an ISG, LY6E, promotes infection by various viruses such as flaviviruses (e.g., West Nile virus, yellow fever virus, dengue virus, and Zika virus), influenza A virus, and HIV-1." (PMID 35468127, 2022). "It has been shown that the level of LY6E expression varies following infection by different viruses and that in some cases, it can actually promote further infection." (PMID 35631059, 2022). "LY6E expression was first noted to be modulated upon infection of cells with mouse adenovirus type 1 (MAV-1) and a naturally occurring oncogenic avian herpesvirus, Marek’s disease virus (MDV)." (PMID 35631059, 2022). "Further study is warranted to clarify the distinct roles of LY6E in regulating infection with SARS-CoV-2 and other viruses." (PMID 35907817, 2022). "Lymphocyte antigen 6 family member E (LY6E) potently restricts infection by multiple CoVs, including MHV and several HCoVs (229E, OC43, MERS-CoV, SARS-CoV, SARS-CoV-2)." (PMID 34696406, 2021). "Expression of LY6E in the absence or presence of TMPRSS2 significantly inhibited the infection of all the COVpp, except for SARSpp, which was only significantly inhibited in the presence of TMPRSS2 expression." (PMID 32641482, 2020). "While overexpression of LY6E in C3A and A549 cells efficiently inhibited the infection of HCoV-OC43, knockdown of LY6E expression in HepG2 significantly increased its susceptibility to HCoV-OC43 infection." (PMID 32641482, 2020). "In regard to the immune system, the upregulation of LY-6E is thought to be part of a compensatory mechanism against pathological dysfunction following infection." (PMID 31185901, 2019).
infection (continued). "Infection of LY6E KO or WT U2OS with biotinylated IAV revealed equivalent levels of viral internalization." (PMID 30190477, 2018). "When bafA was added as early as 10 min post-infection, a greater number of LY6E-expressing cells had nuclear vRNP as compared to control cells." (PMID 30190477, 2018). "Several chemokines Ccl2, Ccl5 and Ccl6, and genes from the lymphocyte antigen 6 superfamily, Ly6a, Ly6e and Ly6f were found to be modulated only with V3000 infection in brain." (PMID 28446152, 2017). "In our study, we performed focused CRISPR screens targeting 193 known and predicted GPI-APs and identified LY6E as the key downstream effector of the GPI biosynthesis pathway we found in our larger genome-wide screen in restricting the infection of multiple coronaviruses." (PMID 40901862, 2025). "Notably, the role of each of the five genes (ITGAM, IRF-9, LY6E, PSTPIP2, and RUNX1) has been linked to response to infection in the literature." (PMID 36900096, 2023). "Notably, BATF2 was shown to promote inflammation in response to lipopolysaccharides or infection, and LY6E plays a role in T-cell activation and is upregulated by interferons." (PMID 36077244, 2022). "Moreover, LY6E is up-regulated in the CD4+ T cells of HIV-1-infected individuals during the chronic phase of infection." (PMID 35468127, 2022). "We also showed that an ISG, LY6E, has the ability to promote cell-free infection." (PMID 35468127, 2022). "However, the same group recently reported that LY6E overexpression suppresses HIV-1 (strain NL4-3) infection in Jurkat cells but enhances it in SupT1 cells." (PMID 35468127, 2022). "Therefore, CC viruses may have been selected to be able to utilize the ISGs, including LY6E, that potently promote cell-free infection (bottom)." (PMID 35468127, 2022). "This was already suggested by hierarchical clustering in the analysis of the top 500 most variable genes, and could be indicative of a different progression of the infection impact on both organs, which could be modulated by gene Ly6E, at least for the spleen samples." (PMID 32708319, 2020). "Other genes that increased infection efficiency by ≥4-fold upon knockout included MOSPD2, P4HB, and LY6E (each leading to an approximately 4-fold increase) and IRX2 (an approximately 8-fold increase)." (PMID 40901862, 2025). "Two mRNAs were down-regulated in all treatment groups at the later time points post-infection, namely, CNTNAP1 and NR4A1, while twenty mRNAs were up-regulated in all later time point treatment groups, including IFI6, LY6E, MX1, OASL, STAT1, and CMPK2." (PMID 38675946, 2024). "We further detected 28 of the ISG expression levels upon H37Rv infection at multiplicities of infection 2 (MOI = 2) for 6, 24, and 48 h and approximately 90% (25 out of 28) of the ISGs (except for LY6E, RTP4, and TREX1) were significantly increased in hMDMs." (PMID 30717477, 2019). "Recently, LY6E was shown to impair infection by SARS-CoV, SAR-CoV-2, and MERS-CoV by inhibiting the S-protein-mediated membrane fusion, and mice lacking LY6E expression in immune cells were highly susceptible to mouse hepatitis virus, also a coronavirus." (PMID 35907817, 2022). "We demonstrate here that LY6E promotes infection by several viral families, but that the phenotype does not extend to all enveloped viruses." (PMID 30190477, 2018). "While the expression of ADAP2 and GILT did not inhibit HCoV-OC43pp infection, expression of LY6E in Flp-In TREx 293 cells efficiently suppressed the infection of lentiviral particles pseudotyped with the envelope glycoproteins of all the human CoVs, except for SARSpp." (PMID 32641482, 2020). "However, in the presence of tet to induce LY6E expression, the TMPRSS2-enhanced infection of SARSpp, but not SARS-CoV-2pp, MERSpp, and 229Epp, was significantly diminished." (PMID 32641482, 2020).
tumor (30 papers, 2013 to 2026). "Through integrative bioinformatics approaches, we identified LY6E, an interferon-stimulated gene, as a key mediator of PARPi resistance, with its expression linked to an immunosuppressive tumor microenvironment (TME) encouraging tumor progression and invasion." (PMID 39408764, 2024). "The primary function of LY6E has been associated with immune regulation, specifically in modulating T cell activation, proliferation, development, tumor metastasis, and differentiation." (PMID 31684192, 2019). "In the present study, we provided a novel insight into the regulatory mechanism underlying tumor growth via activation of the LY6E-HIF-1 pathway." (PMID 27589564, 2016). "Importantly, the biological functions of LY6E have been linked to viral infections, immune regulation, and tumor metastases." (PMID 35310607, 2022). "Once tumors reached ~180 mm3, mice were treated with 0.5 or 1.5 mg/kg of anti-Ly6E-CBI or 1.5 mg/kg of anti-Ly6E-MMAE intravenously every 3 weeks up to eight times or until the mice were sacrificed due to body weight loss or overwhelming tumor burden (>1000 mm3)." (PMID 33382956, 2021). "We did detect that LY6E KO clones formed significantly more tumour–NK conjugates compared to LY6E WT cells." (PMID 39642167, 2025). "In T_EP, there was significant upregulation of genes associated with malignancy, such as EPCAM, HSPB1, CEACAM6, MUC1, and LY6E, implicating their roles in tumor initiation." (PMID 40786043, 2025). "Further research, especially in vivo and with single cell resolution, is required to delve deeper into primary and secondary resistance mechanisms and the general role of Ly6A and LY6E in NK cell–mediated tumour surveillance." (PMID 39642167, 2025). "In contrast, Ly6A/LY6E were identified as drivers of tumour evasion by impairing the interaction of NK and tumour cells." (PMID 39642167, 2025). "LY6E interacts with a range of immune cells, including T cells, B cells, dendritic cells, and tumor cells, and these interactions can influence immune checkpoint signaling and contribute to immune suppression." (PMID 39408764, 2024). "We found that many myeloid cell markers were highly expressed in hybrid tumor cells, including Ly6e, Ly6c2, Ccl2, Nos2, Cxcl1, and Cxcl2." (PMID 37138326, 2023). "LY6E is overexpressed in several tumor types, including CRC, and patients with high expression levels of LY6E have a poor prognosis." (PMID 35310607, 2022). "Six diagnostic genes were mutated in descending frequency in the tumor group: COL4A1, ABCA8, MAMDC2, FAP, TMEM100, and LY6E." (PMID 36685898, 2022). "COL4A1, COL6A3, FAP, and LY6E were up-regulated in the tumor group in the training set, whereas ABCA8, MAMDC2, TMEM100, and TMEM266 were down-regulated." (PMID 36685898, 2022). "In summary, we have described efforts to maximize the efficacy and durability of the anti-tumor response for Ly6E-targeted ADCs." (PMID 33382956, 2021). "Another four genes, GBP1, GBP5, LY6E and OAS2, have also been reported to be associated with a variety of other tumor progression." (PMID 33223511, 2020). "The tumor growth assay revealed that the forced expression of LY6E significantly enhanced the growth of HeLa/5HRE-Luc/LY6E tumors more than HeLa/5HRE-Luc/EV tumors xenografted in immunodeficient mice." (PMID 27589564, 2016). "The LY6E-HIF-1 axis functioned to increase tumor blood vessel density and promoted tumor growth in immunodeficient mice." (PMID 27589564, 2016). "We demonstrated that the induction of HIF-1 activity in tumor xenografts as a result of the aberrant expression of LY6E enhanced angiogenesis and malignant tumor growth." (PMID 27589564, 2016). "Our results characterized LY6E as a novel conductor of tumor growth through its modulation of the PTEN/PI3K/Akt/HIF-1 axis and demonstrated the validity of targeting this pathway for cancer therapy." (PMID 27589564, 2016).
tumor (continued). "Optical imaging experiments confirmed that the forced expression of LY6E resulted in high levels of HIF-1 activity during tumor growth both in vivo and in vitro." (PMID 27589564, 2016). "For instance, the MeC derived from the largest IC cluster is highly enriched in interferon response genes, such as ISG15, IFI6, LY6E, and MX1, indicating that the underlying interferon response is among the most common source of transcriptional variation shared across tumor samples and cohorts." (PMID 37149682, 2023). "It was also mentioned that specific antibody–drug conjugates (ADCs) of LY6E could inhibit cell proliferation in vitro and produce durable tumor regression in clinically relevant transplantation models expressing LY6E." (PMID 37259059, 2023). "On the other hand, tumor cells tended to show higher expression of LY6E, FXYD5, and TGFBI." (PMID 35974387, 2022). "The significance of LY6E in tumor growth is attributable to the fact that it might participate in immune regulation, especially for the modulation of T cell activation and proliferation." (PMID 35310607, 2022). "The aberrant expression of LY6E was shown to promote tumor growth by activating HIF-1." (PMID 27589564, 2016). "It was found that LY6E was overexpressed in a multitude of tumor types, including breast, gastric, esophageal, and colorectal tumors, which implies that it might be involved in tumorigenesis and tumor progression." (PMID 35310607, 2022). "Thus, LY6E is an important molecule that can be used to target tumor antigens in multiple cancers." (PMID 35310607, 2022). "However, it currently remains unclear how LY6E promotes malignant phenotypes and accelerates tumor growth." (PMID 27589564, 2016). "We next investigated whether the LY6E-HIF-1 axis promoted tumor growth in vivo." (PMID 27589564, 2016). "LY6/uPAR superfamily members, such as LY6E, LY6H, LY6K, and PSCA, are overexpressed in various cancers and contribute to tumor growth, invasion, and metastasis." (PMID 39727968, 2024). "LY6D, LY6E, PLAUR, PSCA, CD59 and LYPD3 mRNA expression was significantly increased in the PDAC tumor tissues than normal adjacent tissues (p < 0.01)." (PMID 33613843, 2021). "These in vivo results collectively indicated that the aberrant expression of LY6E positively regulated HIF-1 activity, induced angiogenesis, and eventually accelerated tumor growth." (PMID 27589564, 2016). "LY6E’s interaction with the PI3K/Akt pathway, and its subsequent influence on HIF-1α transcription, outlines a mechanism pivotal to pathological processes such as tumor growth and angiogenesis." (PMID 38674087, 2024). "Both anti-Ly6E-CBI and -MMAE conjugates drove single-dose efficacy in xenograft and patient-derived xenograft models, but seco-CBI-dimer conjugates showed reduced tumor outgrowth following multiple weeks of treatment, suggesting that they are less susceptible to developing resistance." (PMID 33382956, 2021). "When conjugated to Ly6E-targeted antibodies, 2 drives enhanced and durable efficacy over more than 5 months, even at doses resulting in tumor stasis rather than regression." (PMID 33382956, 2021). "We believe we were able to enhance tumor accumulation without limiting radial penetration from the vasculature due to the very weak monovalent affinity of anti-Ly6E." (PMID 33382956, 2021). "The anti-Ly6E-CBI conjugate shows substantial inhibition of xenograft growth after a single dose, and in contrast to MMAE conjugates, repeated doses resulting in partial tumor regression do not lead to substantial tumor outgrowth." (PMID 33382956, 2021).
cancer (23 papers, 2016 to 2025). A tumor composed of atypical neoplastic, often pleomorphic cells that invade other tissues. "It was shown that upregulation of LY6E expression was associated with poor prognosis in several cancers, and abnormal overexpression of LY6E was found to increase the expression of the HIF-1α gene mainly at the transcriptional level in mouse models." (PMID 37259059, 2023). "Lymphocyte antigen 6 complex, locus E (LY6E) is abnormally expressed in several cancers and is associated with poor outcomes." (PMID 35310607, 2022). "The Ly6K and Ly6E proteins are implicated as cancer vaccine targets and drug conjugated antibody therapy, respectively suggesting that Ly6 family members can be used as novel candidates to develop targeted therapies." (PMID 26862846, 2016). "Based on accumulating evidence, elucidating the mechanisms underlying the aberrant overexpression of LY6E in cancer cells will provide an insight into the development of rational strategies that target the LY6E-HIF-1 axis for cancer therapy." (PMID 27589564, 2016). "Lymphocyte antigen 6 complex, locus E (LY6E) has been implicated in the malignant progression of various types of cancers; however, the underlying mechanism remains unclear." (PMID 27589564, 2016). "Currently, anti-LY6E antibodies have shown antitumor activity and acceptable safety in phase I trials of refractory malignant tumors (NCT02092792)." (PMID 40308607, 2025). "This study shows that leukaemic cells are actively shaped by NK cells and unravels what we believe to be novel cancer evasion strategies by identifying potential driver genes in mice (Ly6a) and humans (LY6E)." (PMID 39642167, 2025). "Further analysis of the TCGA BRCA data revealed a positive correlation between CCL5 and LY6E level in cancer tissues." (PMID 40634316, 2025). "To investigate the correlation between CCL2/7/8 levels and Sca-1 expression levels, we analyzed TCGA BRCA data and saw a positive correlation between CCL2/7/8 or CXCL1 expression level and LY6E expression in cancer tissues." (PMID 40634316, 2025). "The expression levels of LY6E have been correlated with diminished survival rates across various cancers, accentuating its potential as both a prognostic indicator and a therapeutic target." (PMID 38674087, 2024). "In this study, we found that LY6E expression was upregulated in ten types of cancers using bioinformatic analysis and biologic validation, and these results are in accordance with those of previous studies." (PMID 35310607, 2022). "On a clinical level, high LY6E expression correlates with poor overall patient survival in various malignant tumors such as those of gastric, breast, head and neck, lung, bladder, brain, and skin origin." (PMID 33613843, 2021). "We were particularly interested in studying those genes that are associated with cancer progression, TME signals, and poor prognosis such as LY6E, NAPSA, MUC1, ELF3, and FOS." (PMID 33144684, 2021). "LY6E, an ISG, has been implicated in the TGF-β-mediated escape from immune surveillance in many forms of cancer." (PMID 30642035, 2019). "To examine the status of Ly6E in human cancer, we used Oncomine or G-DOC to analyze gene expression omnibus (GEO) datasets." (PMID 26862846, 2016). "Identifying the critical step is crucial for fully understanding the molecular mechanisms underlying the LY6E-mediated activation of HIF-1, which will, in turn, assist in developing inhibitors of the LY6E-HIF-1 axis for cancer therapy." (PMID 27589564, 2016). "To confirm our results in human cancers, we analyzed the relationship between LY6E expression levels and poor prognoses using the PrognoScan database." (PMID 27589564, 2016). "Taken together, these results justified exploiting LY6E as a prognostic marker as well as a therapeutic target for cancers." (PMID 27589564, 2016). "Diminished expression of LY6E augments cancer cell apoptosis." (PMID 40535808, 2025).